IFI30 (IFI30 lysosomal thiol reductase)
Description:
Lysosomal thiol reductase that catalyzes protein disulfide bonds reduction. Plays an important role in antigen processing and presentation, of namely both major histocompatibility complex (MHC) class I- and class II-restricted antigen by reducing the disulfide bonds of endocytosed proteins and facilitating their unfolding and optimal degradation. Shares with thioredoxin a reduction mechanism in which the N-terminal cysteine thiol group in the CXXC active site motif initiates a nucleophilic attack on the substrate disulfide bond,resulting in the formation of a mixed disulfide-linked enzyme-substrate intermediate (Probable). Subsequent intramolecular attack by the second cysteine thiol group enables the release of the reduced substrate and oxidized enzyme (Probable). Lysosomal cysteine is a physiological reducing agent that is capable of reducing IFI30, so that it can catalyzes the next reaction. Dithiothreitol, cysteine, and cysteinyl glycine, but not glutathione, are capable of regenerating active precursor and mature IFI30 in vitro.
Synonyms: GILT; IP30; IFI-30; MGC32056; IP-30
Tractability: Antibody: UniProt places it where antibodies can reach, with high confidence; its Gene Ontology location is reachable by antibodies, with high confidence; UniProt predicts a signal peptide or a membrane-spanning region. PROTAC: its protein half-life has been measured.
Gene: Protein-coding gene on chromosome 19 (18,173,162 to 18,178,121, forward strand). Ensembl gene ENSG00000216490.
Subcellular location: Secreted; Lysosome
Subcellular location (Human Protein Atlas): Cytosol; Vesicles
Pathways (Reactome):
Immune System: Interferon gamma signaling; MHC class II antigen presentation
Gene Ontology:
Molecular function: oxidoreductase activity, acting on a sulfur group of donors; oxidoreductase activity, acting on a sulfur group of donors, disulfide as acceptor; protein binding
Biological process: antigen processing and presentation of exogenous peptide antigen via MHC class I; antigen processing and presentation of exogenous peptide antigen via MHC class II
Cellular component: extracellular region; lysosome; lysosomal lumen
Genetic constraint (gnomAD): Loss-of-function variants: 26 observed, 23.99 expected, observed/expected ratio (o/e) 1.08, 90% interval 0.79 to 1.5. The synonymous counts are far from expectation, so gnomAD's model fits this gene poorly and the ratio says little. Missense variants: 296 observed, 270.09 expected, observed/expected ratio (o/e) 1.1, 90% interval 1 to 1.21. Synonymous variants: 149 observed, 118.52 expected, observed/expected ratio (o/e) 1.26, 90% interval 1.1 to 1.44.
Homologues: Orthologues: chimpanzee IFI30 (99% identical), macaque IFI30 (91% identical), dog IFI30 (68% identical), pig IFI30 (68% identical), rat Ifi30 (64% identical), mouse Ifi30 (62% identical), guinea pig IFI30 (61% identical), tropical clawed frog ifi30 (43% identical), Caenorhabditis elegans C02D5.2 (24% identical), Drosophila melanogaster CG41378 (24% identical).
Diseases named in the same sentence as IFI30 in open-access papers:
IFI30 is named in the same sentence as 68 diseases in open-access papers, as found by Europe PMC text mining. Sharing a sentence is not in itself a finding about the gene and the disease. The quoted sentences say what the papers report.
melanoma (27 papers, 2009 to 2025). A malignant, usually aggressive tumor composed of atypical, neoplastic melanocytes. "IFI30 is upregulated in breast cancer and melanoma and has been linked to disease progression in prostate cancer." (PMID 37784035, 2023). "Published research studies on IFI30, the gene coding for the enzyme that is functionally associated with antigen processing, have been mainly performed on melanoma, breast cancer, and diffuse large B‐cell lymphoma (DLBCL)." (PMID 32969157, 2020). "Notably, the role of IFI30 appears to be context‐dependent in various cancer types: in glioma, elevated IFI30 expression is associated with poor prognosis, whereas in melanoma and diffuse large B‐cell lymphoma, it correlates with better survival outcomes." (PMID 40186402, 2025). "Elevated expression levels of IFI30 have been associated with improved patient survival in several cancers, including diffuse large B‐cell lymphoma, gastroesophageal junction adenocarcinoma, melanoma, and cervical cancer." (PMID 40186402, 2025). "Recent research has demonstrated that IFI30 is aberrantly expressed in various cancers, including breast cancer, melanoma, and glioma." (PMID 40186402, 2025). "With the in‐depth study of IFI30, it has been found that it also plays an important role in the occurrence and development of various cancers, such as malignant melanoma, hematopoietic malignancies, and breast cancer." (PMID 37408388, 2023). "IFI30 can promote breast cancer proliferation, migration and invasion through cellular autophagy, and promote melanoma development by modulating tolerance to autoantigens." (PMID 37035172, 2023). "Recent researches have revealed that IFI30 plays an indispensable role in the immune response of malignant tumors, such as melanoma, prostate cancer and glioma 16-18." (PMID 34400904, 2021). "The study of Kenneth H. Buetow showed high expression of IFI30 and an active and intact class II MHC antigen presentation pathway was associated with improved melanoma survival." (PMID 34400904, 2021). "The IFI30 expression, in melanoma and squamous cell carcinoma, has been shown to enhance antigen presentation and to activate CTSB, which is required for osteoclast fusion during differentiation." (PMID 20551950, 2010). "By way of example, in melanoma, IFI30 could boost the processing and presentation of tumor antigens, TRP1 and TRP2, resulting in enhanced anti-tumor T-cell responses and ultimately higher patient survival." (PMID 37215115, 2023). "In addition, IFI30 is found to be upregulated in some metastatic tumor types, such as melanoma and glioma." (PMID 35910561, 2022). "Additionally, some investigations have also explored the relationship between IFI30 and cancer, revealing that IFI30 expression exhibits a robust relationship with immune cell infiltration and the prognosis of prostate cancer, melanoma, breast cancer, and glioma." (PMID 37991414, 2024). "IFI30 expression can induce other cell types through interferon-gamma (IFN-γ), such as melanoma cell lines." (PMID 37991414, 2024). "In addition, recent studies have revealed the aberrant expression of IFI30 in several types of cancers, such as diffuse large B‐cell lymphoma (DLBCL), melanoma, and breast cancer." (PMID 37408388, 2023).
glioma (21 papers, 2018 to 2025). A benign or malignant brain and spinal cord tumor that arises from glial cells (astrocytes, oligodendrocytes, ependymal cells). "Analysis of public databases and glioma tissues showed that IFI30 was an independent predictor for glioma, as high IFI30 mRNA expression was associated with poor patient outcomes." (PMID 37408388, 2023). "For example, IFI30 overexpression is linked to the occurrence of high-grade tumors, immune infiltration, and worse OS in glioma." (PMID 36741315, 2023). "We further examined IFI30 protein expression levels in clinical glioma samples and obtained the same results, confirming that IFI30 was highly expressed in glioma tissues and was associated with poor outcomes." (PMID 37408388, 2023). "All the results demonstrated the association between IFI30 expression and the malignant phenotype of gliomas." (PMID 32969157, 2020). "IFI30 is highly expressed in glioma and associated with chemotherapy response." (PMID 33644115, 2021). "IFI30 predominantly localizes within monocyte/macrophage populations and exhibits a strong correlation with the immune infiltration of glioma." (PMID 41438761, 2025). "Of the genes identified by LASSO analysis, APOC1 and IFI30 expression levels in glioma were favorably correlated with the majority of immune cells, immunostimulators, immunoinhibitors, MHC molecules, chemokines, and chemokine receptors." (PMID 41438761, 2025). "Conversely, IFI30 expression has shown an inverse relationship with survival outcomes in other malignancies, including glioma, prostate cancer, and gastric cancer." (PMID 40186402, 2025). "A recent study similarly indicated that IFI30 increased resistance to temozolomide, while its knockdown boosts temozolomide‐induced apoptosis in glioma cells." (PMID 40186402, 2025). "ZNF384, being a transcription factor of IFI30, then promotes the expression of IFI30, ultimately leading to the enhancement of glioma stemness." (PMID 38967893, 2024). "Real-time quantitative polymerase chain reaction (RT-qPCR) analysis revealed high expression levels of lncRNA linc00265 and lysosomal thiol reductase (IFI30) in glioma cells." (PMID 38967893, 2024). "It has been reported that IFI30 can promote the EMT process in glioma cells by activating EGFR/AKT/GSK3β/β-catenin." (PMID 38517387, 2024). "Taken together, these data suggest that IFI30 promotes the proliferation, migration, and invasion of glioma cells." (PMID 37408388, 2023). "Public datasets, immunohistochemistry, and western blotting (WB) were used to evaluate the expression of IFI30 in glioma." (PMID 37408388, 2023). "Given the upregulation of IFI30 in glioma and its ability to predict survival, we next explored the biological function of IFI30." (PMID 37408388, 2023). "Bioinformatics analysis in this study of an online public database indicated that IFI30 was highly expressed in glioma samples." (PMID 37408388, 2023). "Functionally, both in vivo and in vitro evidence showed that IFI30 regulated the migration and invasion of glioma cells." (PMID 37408388, 2023). "The results of GEPIA also showed that the expression of IFI30 was significantly enriched in GBM versus low‐grade glioma, and the expression of IFI30 was higher in glioma tissues than in adjacent tissues." (PMID 37408388, 2023). "The immunohistochemistry (IHC) results also revealed that IFI30 expression was increased with increasing WHO grade of glioma and was higher than that in NBTs." (PMID 37408388, 2023). "IFI30 was significantly upregulated in glioma tissues and cell lines compared with corresponding controls, and the expression level of IFI30 was positively associated with tumor grade." (PMID 37408388, 2023). "Functionally, IFI30 promoted the proliferation, migration, and invasion of glioma cells in vitro, and its expression significantly enhanced the growth of glioma in vivo." (PMID 37408388, 2023). "Inhibition of Slug reversed the IFI30 overexpression‐induced increase in the survival rate of glioma cells." (PMID 37408388, 2023).
glioma (continued). "To explore the role of IFI30 in inducing the EMT‐like process, we analyzed glioma subtype‐specific IFI30 expression in the TCGA." (PMID 37408388, 2023). "First, we found that IFI30 mRNA levels were significantly elevated in response to TMZ in glioma cells." (PMID 37408388, 2023). "We used the CCK‐8 assay to detect the survival rate of IFI30‐silenced glioma cells and IFI30‐overexpressing cells treated with different concentrations of TMZ." (PMID 37408388, 2023). "In conclusion, IFI30, an independent predictor of glioma prognosis, is overexpressed in glioma, and its expression is positively correlated with tumor grade." (PMID 37408388, 2023). "In contrast, we overexpressed IFI30 in glioma cells to further investigate the regulatory role of IFI30 in glioma progression." (PMID 37408388, 2023). "We demonstrated that IFI30 was highly expressed in glioma tumors and cell lines, and its expression was negatively correlated with the prognosis of patients." (PMID 37408388, 2023). "The results showed that the mRNA expression level of EGFR was significantly decreased in IFI30‐silenced glioma cells but increased in IFI30‐overexpressing cells." (PMID 37408388, 2023). "Study demonstrated that lentivirus mediated IFI30 inhibited the proliferation of human glioma U373MG cell." (PMID 34400904, 2021). "In glioma, IFI30 was highly expressed in glioblastomas and gliomas with mesenchymal subtypes or wild-type isocitrate dehydrogenase, which indicated that gliomas were highly malignant and had poor prognosis." (PMID 34400904, 2021). "Our comprehensive study on IFI30 in gliomas found its expression to be high in glioblastomas and in gliomas with a mesenchymal subtype or wild‐type isocitrate dehydrogenase, all of which indicated the malignancy and poor outcomes of gliomas." (PMID 32969157, 2020). "In summary, we have conducted a comprehensive research study on IFI30 expression in gliomas and ascertained through bioinformatic profiling that this gene would be an unfavourable prognostic predictor of this disease." (PMID 32969157, 2020). "Our results showed that gliomas with higher IFI30 expression were more infiltrated by M0 macrophages and Tregs, whereas their infiltration by CD8 T cells did not increase correspondingly." (PMID 32969157, 2020). "To clarify the characteristics of IFI30 in gliomas, we first analysed its expression level in the CGGA and TCGA data sets stratified according to the tumour grade, isocitrate dehydrogenase (IDH) mutation status, and 1p/19q codeletion status." (PMID 32969157, 2020). "The IFI30 expression level in different grades of gliomas was also confirmed by immunohistochemical staining." (PMID 32969157, 2020). "The gliomas were next divided into mesenchymal and non‐mesenchymal subtype groups for ROC curve analysis, which showed the high efficiency of the IFI30 expression level in predicting the mesenchymal subtype." (PMID 32969157, 2020). "Further analysis of available open-access glioma single-cell sequencing data revealed that IFI30 expression was positively correlated with immune cells and, echoing the conclusions drawn above, that macrophage composition made up a large proportion of these immune cells." (PMID 39925804, 2025). "In this study, the effect of IFI30 on glioma was investigated." (PMID 37408388, 2023). "GSEA indicated that AKT was significantly correlated with IFI30 expression in glioma." (PMID 37408388, 2023). "The GSEA results showed that AKT was significantly correlated with IFI30 expression in glioma." (PMID 37408388, 2023). "In addition, IFI30 regulated the chemoresistance of glioma cells to temozolomide directly via the expression of the transcription factor Slug, a key regulator of the EMT‐like process." (PMID 37408388, 2023). "Importantly, we found that IFI30 regulated the chemoresistance of glioma cells to TMZ directly via the expression of the transcription factor Slug, a key regulator of EMT." (PMID 37408388, 2023).
glioma (continued). "We found that silencing IFI30 significantly decreased the viability of glioma cells." (PMID 37408388, 2023). "CCK‐8 and colony formation assays confirmed the findings that IFI30 overexpression could induce the proliferation of glioma cells compared to that in the NC group." (PMID 37408388, 2023). "Moreover, inhibition of IFI30 promoted the apoptosis of glioma cells treated with various concentrations of TMZ, as detected by flow cytometry, while overexpression of IFI30 suppressed the apoptosis of glioma cells treated with certain TMZ concentrations." (PMID 37408388, 2023). "However, the absence of the lymphatic system and the existence of the blood–brain barrier in the CNS prevent IFI30 from inducing antitumor immunity in glioma." (PMID 37408388, 2023). "Moreover, IDH wild‐type GBM patients were divided into an IFI30 high‐expression group and a low‐expression group according to the median IFI30 expression level in glioma patients from the CGGA and TCGA databases." (PMID 37408388, 2023). "Our study provided solid evidence that IFI30 might be a novel regulator of the EMT‐like process in glioma and explains why the high expression of IFI30 in glioma can promote tumor growth." (PMID 37408388, 2023). "Overexpression of IFI30 dramatically increased the survival rate of glioma cells." (PMID 37408388, 2023). "In addition, we found that IFI30 knockdown reduced the levels of cytosolic and nuclear β‐catenin in glioma cells, while IFI30 overexpression increased the expression of β‐catenin." (PMID 37408388, 2023). "In addition, IFI30 promoted the EMT‐like process in gliomas via the EGFR/AKT/GSK3β/β‐catenin signaling pathway both in vitro and in vivo." (PMID 37408388, 2023). "Furthermore, the correlation analysis indicated that the expression of IFI30, an acknowledged biomarker in glioma, was positively correlated with HLA-DMA, P4HB and RCN1." (PMID 35436915, 2022). "IFI30 has been known as a prognosis factor for many cancers, such as glioma and breast cancer." (PMID 36387234, 2022). "IFI30 is the most stable prognostic gene among interferon-stimulated genes in glioma." (PMID 33579282, 2021). "Chen Zhu's study presented that IFI30 was highly expressed in malignant subtypes of glioma, and could reduce the chemosensitivity of glioma cells by activating the IL6-STAT6 signaling pathway." (PMID 34400904, 2021). "All these research reports underscore the possibilities and potentials of targeting TAMs in glioma treatment, and our results imply that patients with high IFI30 expression might benefit most from such therapy." (PMID 32969157, 2020). "Given that IFI30 participates in MHC II‐associated antigen processing, the discovery that its high expression implied poor outcomes for patients with gliomas prompted us to explore the relationship between IFI30 expression and immune cell infiltration by applying the ESTIMATE algorithm." (PMID 32969157, 2020). "In this study, we systematically analysed IFI30 in 921 glioma samples sourced from the Chinese Glioma Genome Atlas (CGGA) and The Cancer Genome Atlas (TCGA) databases, including its expression in different tumour grades and subtypes, potential biological functions, and prognostic significance." (PMID 32969157, 2020). "The suggested correlation between high IFI30 expression and an immunosuppressive phenotype contributes to our knowledge about the glioma microenvironment and might provide clues for the development of novel therapeutic targets." (PMID 32969157, 2020). "In addition, IFI30 directly modulates drug resistance in glioma cells." (PMID 38517387, 2024). "Furthermore, we demonstrated that IFI30 promoted the proliferation and migration of glioma cells." (PMID 37408388, 2023). "Additionally, Western blotting (WB) results showed that the protein levels of IFI30 in fresh glioma tissues were significantly higher than those in NBTs, especially in WHO grade 3 and 4 gliomas, and the protein levels were higher in most glioma cells than in NHA cells." (PMID 37408388, 2023).